SLC44A5 (solute carrier family 44 member 5)
Description:
Choline/H+ antiporter.
Synonyms: CTL5; MGC34032
Tractability: Antibody: UniProt places it where antibodies can reach, with high confidence; its Gene Ontology location is reachable by antibodies, with high confidence; UniProt predicts a signal peptide or a membrane-spanning region.
Gene: Protein-coding gene on chromosome 1 (75,202,129 to 75,611,114, reverse strand). Ensembl gene ENSG00000137968.
Subcellular location: Cell membrane
Subcellular location (Human Protein Atlas): Cytosol
Pathways (Reactome):
Metabolism: Synthesis of PC
Transport of small molecules: SLC-mediated bile acid transport
Gene Ontology:
Molecular function: choline transmembrane transporter activity; protein binding; transmembrane transporter activity
Biological process: choline transport; bile acid and bile salt transport; phosphatidylcholine biosynthetic process; transmembrane transport
Cellular component: plasma membrane
Genetic constraint (gnomAD): Loss-of-function variants: 29 observed, 45.69 expected, observed/expected ratio (o/e) 0.63, 90% interval 0.47 to 0.87. The upper end of that interval is the gene's LOEUF score, 0.87, which puts it in group 3 of 6, group 1 being the genes least tolerant of losing a copy. Missense variants: 404 observed, 474.11 expected, observed/expected ratio (o/e) 0.85, 90% interval 0.79 to 0.93. Synonymous variants: 136 observed, 164.45 expected, observed/expected ratio (o/e) 0.83, 90% interval 0.72 to 0.95.
Homologues: Orthologues: chimpanzee SLC44A5 (97% identical), macaque SLC44A5 (95% identical), pig SLC44A5 (77% identical), rabbit SLC44A5 (76% identical), dog SLC44A5 (75% identical), rat Slc44a5 (69% identical), mouse Slc44a5 (69% identical), guinea pig SLC44A5 (68% identical), tropical clawed frog slc44a5 (65% identical), zebrafish slc44a5b (62% identical), zebrafish slc44a5a (60% identical). Paralogues in human: SLC44A2 (54% identical), SLC44A4 (46% identical), SLC44A1 (26% identical), SLC44A3 (25% identical).
Diseases named in the same sentence as SLC44A5 in open-access papers:
SLC44A5 is named in the same sentence as 12 diseases in open-access papers, as found by Europe PMC text mining. Sharing a sentence is not in itself a finding about the gene and the disease. The quoted sentences say what the papers report.
dystocia (2 papers, 2012 to 2025). Slow or difficult obstetric labor or childbirth. "In this study, we identified a SNP in the 5′ UTR of SLC44A5 that is correlated with birth weight in cattle and with the rate of dystocia; cows carrying the G polymorphism express this gene at higher levels." (PMID 22815983, 2012). "For instance, a polymorphism at the 5’ UTR of SLC44A5 was found to be associated with birth weight in Holsteins and thus could be considered to control dystocia in cattle." (PMID 40660125, 2025). "Our work identified that SLC44A5 is a critical mediator of birth weight and that SLC44A5 might be a useful target for preventing dystocia." (PMID 22815983, 2012). "This study provides novel insights into the molecular mechanisms that control birth weight in Holsteins and suggests that SLC44A5 may serve as a potential target for preventing dystocia." (PMID 22815983, 2012).
Obesity (1 paper, 2025). Accumulation of substantial excess body fat. "Three of the common DEGs altered by obesity in all NVU cell types (Slc44a5, Gria1, and Shisa6) play a key role in neurotransmission." (PMID 41310161, 2025).
osteosarcoma (1 paper, 2023). A usually aggressive malignant bone-forming mesenchymal neoplasm, predominantly affecting adolescents and young adults. "Several amino acid transporters, such as SLC44A5, SLC9B2, and SLC37A2, were significantly decreased after NACT, which might contribute to the amino acid deprivation in osteosarcoma after NACT." (PMID 37457661, 2023).
tumor (1 paper, 2020). "It was observed that both miR-144-5p and miR-144-3p had tumor inhibitory effects by targeting several oncogenes in squamous NSCLC including neuronal calcium sensor 1 (NCS1), solute carrier family 44 member 5 (SLC44A5), and myristoylated alanine rich protein kinase C substrate (MARCKS) genes." (PMID 32276343, 2020).
SLC44A5 also shares sentences with these, for which no sentence is quoted: cardiovascular disease (1 paper); developmental delay (1); infection (1); Insulin resistance (1); metabolic syndrome (1); small cell lung carcinoma (1); transient ischemic attack (1); type 2 diabetes (1).